SIRT1 (sirtuin 1)
Diseases named in the same sentence as SIRT1 in open-access papers (continued):
Sharing a sentence is not in itself a finding about the gene and the disease.
schizophrenia (continued). "Future longitudinal studies are needed to confirm the role of SIRT1 involved in the pathogenesis of MetS in schizophrenia patients and to further reveal its immune-inflammatory mechanism." (PMID 33324265, 2020). "In conclusion, RSV showed neuroprotective effect on MK-801-induced schizophrenia rat model through regulating SIRT1 and downstream BDNF expression in the hippocampus." (PMID 32793005, 2020). "In summary, RSV showed a neuroprotective effect in the MK-801-induced schizophrenia rat model through activating the SIRT1/CREB/BDNF signaling pathway in the hippocampus." (PMID 32793005, 2020). "In this research, the depressed expression of SIRT1 in the neonatal rat schizophrenia model was elevated by the administration of RSV." (PMID 32793005, 2020). "Our preliminary findings provide suggestive evidence that SIRT1 makes schizophrenia patients more prone to depressive symptoms." (PMID 32849821, 2020). "Meanwhile, qt-PCR was used to detect the mRNA levels of SIRT1 in peripheral blood of 197 olanzapine monotherapy schizophrenia patients." (PMID 32849821, 2020). "Our results identified the IL-6 × SIRT1 (β = −0.463, t = 10.040, P = 0.002) as the influencing factor for the MetS in schizophrenia patients." (PMID 33324265, 2020). "Our correlation analysis showed that SIRT1 was significantly correlated with diastolic blood pressure, triglyceride, and high-density lipoprotein cholesterol in schizophrenia patients." (PMID 33324265, 2020). "Our preliminary study provides evidence suggesting that schizophrenia patients with MetS exhibited reduced plasma SIRT1 but increased inflammatory cytokines levels compared to the non-MetS patients." (PMID 33324265, 2020). "Another protein that appears to have a connection with the symptoms of schizophrenia is SIRT1 (Sirtuin 1), a nicotinamide-dependent deacetylase (NAD+) widely involved in glucose homeostasis, DNA repair, apoptosis, inflammation, and differentiation." (PMID 31614739, 2019). "Similarly, resveratrol and subsequent SIRT1 activation have demonstrated positive effects in protecting against cognitive impairments in a young mouse schizophrenia model." (PMID 39404407, 2024). "Decreased levels of SIRT1 in plasma has been linked with a higher comorbidity of depressive symptoms, whereas increased levels of DNMT1 had been observed in the brains of schizophrenia and bipolar patients." (PMID 36768211, 2023). "First and foremost, we analyzed the effect of only one SNP in SIRT1 on schizophrenia." (PMID 32849821, 2020). "Therefore, RSV treatment ameliorates the depressed CREB/BDNF pathway in the neonatal rat schizophrenia model through enhancing SIRT1 expression." (PMID 32793005, 2020). "In this study, we found neither the association between SIRT1 mRNA expression in the brain and schizophrenia nor the significant effect of the rs3758391 polymorphism on susceptibility to schizophrenia in PGC GWAS." (PMID 32849821, 2020). "It suggests that the SIRT1 SNP rs3758391 probably does not confer an increased risk of schizophrenia." (PMID 32849821, 2020). "In summary, we speculated that the effect of SIRT1 on the development of depressive symptoms in schizophrenia might be achieved by regulating the inflammatory response." (PMID 32849821, 2020). "Taken together, decreased SIRT1 may bring out MetS in schizophrenia patients through the activation of inflammatory pathways." (PMID 33324265, 2020). "In this study, we hypothesized that the SIRT1 SNP rs3758391 might be a hazard for schizophrenia pathogenesis, especially related to the appearance of depressive symptoms." (PMID 32849821, 2020). "Although no study to date has explored the association of peripheral SIRT1 and metabolic abnormalities in schizophrenia, an early study demonstrated that atypical antipsychotics could downregulate the expression of SIRT1 and interfere with the SIRT1 pathway." (PMID 33324265, 2020).
schizophrenia (continued). "Thus, we hypothesized that the high incidence of metabolic dysregulation in schizophrenia patients may be related to the abnormality of SIRT1." (PMID 33324265, 2020). "Moreover, the T-allele of SIRT1 rs2273773 was seen, as part of two haplotypes of SIRT1, to be associated with schizophrenia but not with bipolar disorder." (PMID 26509718, 2015). "In summary, we report that penfluridol, a drug for treating schizophrenia in the clinic, can suppress mitochondrial OXPHOS through targeting the SIRT1/PGC-1α axis to reduce ATP production, especially in mutant KRAS-expressing NSCLC cells." (PMID 35681729, 2022). "In the hippocampus of MK-801-induced schizophrenia rat model, RSV enhanced silent information regulator 1 (SIRT1) and brain derived neurotrophic factor (BDNF) expression and alleviated oxidative stress." (PMID 32793005, 2020). "However, there were no other significant correlations between SIRT1, IL-6, and IL-10 levels and MetS components in schizophrenia patients (all P > 0.05)." (PMID 33324265, 2020). "Finally, due to the inherent characteristics of cross-sectional studies, we failed to determine whether SIRT1 levels have changed before the onset of depressive symptoms in schizophrenia." (PMID 32849821, 2020).
alcoholic liver diseases (17 papers, 2016 to 2025). A disorder caused by damage to the liver parenchyma due to alcohol consumption. "Ethanol feeding causes alcoholic liver disease (ALD) via the suppression of AMPK activation and cytoplasmic Sirt-1, and administration of dihydromyricetin (5 mg/kg) for 8 weeks can reversed this process." (PMID 34656137, 2021). "Targeting intestinal SIRT1 or alleviating ferroptosis signals in the liver may offer promising avenues for the treatment of human alcoholic liver disease." (PMID 40109363, 2025). "Interestingly, targeting intestinal SIRT1 has also been proposed as a novel approach for treating alcoholic liver disease by reducing liver ferroptosis." (PMID 40109363, 2025). "Consistent with our results, a recent report showed that Sirt1 protein expression could be induced by treatment of A549 cells with a water extract of KRG at 500 μg/mL; moreover, feeding with KRG at 250 and 500 mg/kg for 4 weeks increased the expression of Sirt1 in alcoholic liver disease model mice." (PMID 31672931, 2019). "Furthermore, BRD4 can repress antifibrotic factors; in alcoholic liver disease, BRD4 binding to the SIRT1 promoter suppresses SIRT1 expression, which leads to impaired autophagy and heightened TGF-β signaling." (PMID 40149956, 2025).
lymphoma (17 papers, 2011 to 2024). A malignant (clonal) proliferation of B- lymphocytes or T- lymphocytes which involves the lymph nodes, bone marrow and/or extranodal sites. "In this aspect, abnormal mitoses caused by SIRT1/HSP90 blockade are certainly important contributors to lymphoma cell death." (PMID 37816710, 2023). "Although NAD+ supplementation in A-T models is helpful in overcoming A-T neuropathology by improving NAD+/SIRT1 axis, we suspect NAD+ will fuel tumor proliferation in A-T lymphoma cases associated with increased SIRT3 expression." (PMID 33273545, 2020). "Importantly, SIRT1 and HSP90α formed complexes also in lymphoma cells and the number of SIRT1-HSP90α complexes was significantly higher in OxPhos- dependent than -independent DLBCL cell lines." (PMID 37816710, 2023). "To determine if SIRT3 assists DLBCL cells to resists metabolic stress, we first determined expression of SIRT1, SIRT3 and ATM in human lymphoma samples to understand clinical relevance of these markers in DLBCL." (PMID 33273545, 2020). "Staining of ATM, SIRT1 and SIRT3 in lymphoma patients demonstrated a variation in their degree of expression suggesting a differential requirement of these critical markers during tumor development." (PMID 33273545, 2020). "One possible reason for the absence of lifespan extension in SIRT1-overexpressing mice is that these animals are particularly prone to nonmetabolically related diseases (i.e., lymphoma), independent of SIRT1 dosage." (PMID 23941528, 2014).
tauopathy (17 papers, 2009 to 2025). Neurodegenerative disorders involving deposition of abnormal tau protein isoforms (tau proteins) in neurons and glial cells in the brain. "Sirt1 deacetylates tau, thereby reducing pathogenic tau in mouse models of tauopathy and brain injury." (PMID 40969938, 2025). "A deficiency in SirT1 level has been recently implicated in increased tau acetylation, a dominant post-translational modification and key pathological event in AD and tauopathies." (PMID 30514854, 2018). "Perhaps one of the most important relationships between SirT1 function and the risk for and progression of AD and related tauopathies is deacetylation of tau." (PMID 30514854, 2018). "While SIRT1 exhibits neuroprotective roles in many contexts, its effects in tauopathies are complex." (PMID 40621197, 2025). "A positive correlation between Sirt1 activity and reduction of Aβ plaques and tauopathies was established in various animal models of AD." (PMID 33329577, 2020). "To test the role of sirtuins in the hydralazine-mediated recovery of mitochondrial function in tauopathy cell models, we treated SIRT1 and SIRT5 knockdown AP cells with hydralazine." (PMID 31659167, 2019). "In a mouse model of tauopathy, SIRT1 was shown to deacetylate tau, leading to tau degradation and a reduction in the spread of pathogenic tau." (PMID 30973934, 2019). "Injection of SIRT1 lentivirus in the hippocampus of p25 transgenic mice, a model of AD and tauopathies, protected the mice against neurodegeneration." (PMID 29855513, 2018). "SIRT1 can protect neurons from oxidative stress in mammalian cells, neurotoxicity in cell-based models for AD/tauopathies, ALS, and Wallerian degeneration." (PMID 19173742, 2009). "Intriguingly, our study revealed that nuclear SIRT1 was downregulated in triple tau-mutant iPSCs, which is consistent with the findings reported in human tauopathy brains, where reduced SIRT1 levels were detected and negatively correlated with the amount of hyperphosphorylated tau aggregates." (PMID 37408218, 2023). "Surprisingly, the impact of SIRT1 on the initial stages of tauopathy is inevitable." (PMID 37598127, 2023). "Moreover, Nobiletin, as an activator of SIRT1 signaling pathways, deacetylated p-tau, hence preventing tauopathy." (PMID 37598127, 2023). "The inactivation of sirtuin 1 (SIRT1), an enzyme, leads to the post-translational alteration in tau, specifically acetylation of tau, which acts as a precursor for tau phosphorylation and tauopathy." (PMID 36834835, 2023). "Interestingly, SIRT1 is upregulated in mouse models of AD/tauopathies and ALS and provides a protective effect." (PMID 30973934, 2019). "In contrast, increased SirT1 levels may likely affect levels of acetyl tau and the tauopathy pathway as previously reported." (PMID 30514854, 2018). "In addition, SIRT1 prevents tauopathy by deacetylating tau protein in diabetic models." (PMID 41254180, 2025).
intervertebral disc degeneration (16 papers, 2011 to 2026). "Down-regulation of these miRNAs results in increased levels of SIRT1, which promotes beneficial mitophagy that prevents apoptosis of nucleus pulposus cells and contributes to the attenuation of intervertebral disc degeneration." (PMID 40705152, 2025). "SIRT1 appears to play a key role in homeostasis during the human intervertebral disc degeneration process." (PMID 22152608, 2011). "Furthermore, SIRT1 mitigates IL-1β-induced NLRP3 inflammasome activation in nucleus pulposus cells during intervertebral disc degeneration by promoting mitophagy." (PMID 40705152, 2025). "In intervertebral disc degeneration, circRNA-CIDN was revealed to promote the homeostatic of extracellular matrix through miRNA-34a-5p/SIRT1 axis and inhibit apoptosis, providing a new perspective for the study of the pathogenesis of compression intervertebral disc degeneration." (PMID 35154330, 2022). "In summary, our in vitro and in vivo findings demonstrate that P. acnes inhibits SIRT‐1, thereby inducing impairment of mitochondrial biogenesis and phagocytic activity in NPCs, which ultimately contributes to the development of infectious intervertebral disc degeneration." (PMID 40891515, 2026).
oral cancer (16 papers, 2013 to 2025). "We next addressed the molecular mechanisms underlying SIRT1 inhibition and concurrent cell death by these two compounds in oral cancer cells." (PMID 38567911, 2024). "In contrast, overexpression of SIRT1 in oral cancer cells caused a significant reduction of MMP7 activity, while TGF-β stimulation was slightly reversed the increase in MMP7 activity (p <0.05)." (PMID 25424420, 2014). "Our CETSA- and cell-based results suggested that the targeting and inhibition of SIRT1 by heliomycin provoked autophagy and attenuated the growth of oral cancer cells." (PMID 38567911, 2024). "Our CETSA-based results suggested that the test compounds altered the unfolding and aggregation properties of SIRT1 in response to heat challenge, indicating that both 4-dmH and heliomycin biophysically interact with SIRT1 in oral cancer cells." (PMID 38567911, 2024). "In the present study, we observed upregulation of SIRT1 in tumor tissues of animals and oral cancer patients." (PMID 38567911, 2024). "Using molecular docking simulations and cell-based studies, we herein demonstrated that both 4-dmH and heliomycin targeted SIRT1 and inhibited its activity and expression, to attenuate the growth of oral cancer cells." (PMID 38567911, 2024). "Upon this binding, tNOX is ubiquitinylated and degraded, which in turn attenuates signaling by the tNOX-NAD+-SIRT1 regulatory axis and induces apoptosis in oral cancer cells." (PMID 38567911, 2024). "ITDRFCETSA also indicated that the parental heliomycin engaged with SIRT1 in oral cancer cells, as supported by the positive correlation of SIRT1 heat resistance with the heliomycin concentration." (PMID 38567911, 2024). "We also observed that tNOX and SIRT1 were both upregulated in tumor tissues of oral cancer patients compared to adjacent normal tissues, suggesting their clinical relevance." (PMID 38567911, 2024). "Protein analysis of tissues from oral cancer patients indicated that both tNOX and SIRT1 were upregulated in four out of five tumor samples compared to their adjacent normal tissues." (PMID 38567911, 2024). "Upon this binding, tNOX is ubiquitinylated and degraded, which in turn attenuates signaling by the tNOX-NAD+-SIRT1 regulatory axis and induces apoptosis in oral cancer cells, as evidenced by the results of in vitro and in vivo studies." (PMID 38567911, 2024). "SIRT1 downregulation in oral cancer cells leads to mitochondrial hyperfusion and drug resistance, while SIRT1 overexpression or activation by gallic acid reverses this effect, promoting apoptosis and restoring cisplatin sensitivity." (PMID 39403142, 2024). "Collectively, these results concluded that SIRT1 is downregulated in oral cancer cells under basal and cisplatin resistance conditions." (PMID 37949849, 2023). "The present study showed that SIRT1, a tumor suppressor gene, is downregulated in oral cancer during the therapeutic intervention and facilitates drug resistance." (PMID 37949849, 2023). "The meta-analysis study showed that SIRT1 was found to be downregulated in oral cancer cells under basal as well as CDDP resistance conditions." (PMID 37949849, 2023). "In this study, we have observed that SIRT1 activation led to DNM1L phosphorylation which subsequently controlled mitochondrial hyperfusion to trigger apoptosis in oral cancer cells." (PMID 37949849, 2023). "Arecoline-induced epigenetic markers such as sirtuin-1 hypermethylation, low protein expression of miR-22, and miR-886-3-p accelerate oral cancer progression." (PMID 37190117, 2023). "Further confirmation of SIRT1-regulated apoptosis induction in oral cancer cells was confirmed in GA-primed cells in basal as well as SIRT1 knockdown conditions." (PMID 37949849, 2023). "Some literature data indicated the role of SIRT1 in the regulation of precancerous oral lesions and oral cancer." (PMID 34685718, 2021).